CAPN5 (calpain 5)
Description:
Calcium-regulated non-lysosomal thiol-protease.
Synonyms: nCL-3; HTRA3; ADNIV; VRNI
Tractability: PROTAC: ubiquitination databases record sites on it; its protein half-life has been measured.
Gene: Protein-coding gene on chromosome 11 (77,066,961 to 77,126,155, forward strand). Ensembl gene ENSG00000149260.
Subcellular location (Human Protein Atlas): Nucleoplasm; Cytosol
Pathways (Reactome):
Extracellular matrix organization: Degradation of the extracellular matrix
Gene Ontology:
Molecular function: protein binding; calcium-dependent cysteine-type endopeptidase activity
Biological process: proteolysis; signal transduction
Cellular component: cell surface; extracellular exosome; focal adhesion; cytoplasm; synapse
Genetic constraint (gnomAD): Loss-of-function variants: 54 observed, 72.99 expected, observed/expected ratio (o/e) 0.74, 90% interval 0.59 to 0.93. The upper end of that interval is the gene's LOEUF score, 0.93, which puts it in group 3 of 6, group 1 being the genes least tolerant of losing a copy. Missense variants: 781 observed, 879.14 expected, observed/expected ratio (o/e) 0.89, 90% interval 0.84 to 0.94. Synonymous variants: 334 observed, 357.81 expected, observed/expected ratio (o/e) 0.93, 90% interval 0.85 to 1.02.
Gene-disease validity (ClinGen):
ClinGen rates the evidence that CAPN5 causes each of these diseases.
CAPN5-related vitreoretinopathy (autosomal dominant): Definitive. An autosomal dominant vitreoretinopathy caused by variants in the CAPN5 gene.
Homologues: Orthologues: chimpanzee CAPN5 (99% identical), macaque CAPN5 (98% identical), pig CAPN5 (93% identical), rabbit CAPN5 (93% identical), mouse Capn5 (92% identical), dog CAPN5 (92% identical), rat Capn5 (92% identical), guinea pig CAPN5 (87% identical), tropical clawed frog capn5 (74% identical), zebrafish capn5b (72% identical), zebrafish capn5a (68% identical), Caenorhabditis elegans tra-3 (39% identical), and 7 more. Paralogues in human: CAPN6 (46% identical), CAPN8 (35% identical), CAPN3 (34% identical), CAPN2 (34% identical), CAPN11 (33% identical), CAPN1 (32% identical), CAPN9 (32% identical), CAPN12 (30% identical), CAPN10 (29% identical), CAPN14 (28% identical), CAPN13 (25% identical), ADGB (20% identical), and 8 more.
Diseases named in the same sentence as CAPN5 in open-access papers:
CAPN5 is named in the same sentence as 53 diseases in open-access papers, as found by Europe PMC text mining. Sharing a sentence is not in itself a finding about the gene and the disease. The quoted sentences say what the papers report.
Autosomal dominant neovascular inflammatory vitreoretinopathy (10 papers, 2012 to 2025). "Mutations in CAPN5 cause the devastating eye disease neovascular inflammatory vitreoretinopathy (NIV)." (PMID 40650235, 2025). "Recently, mutations in the Capn5 gene were identified as the cause of neovascular inflammatory vitreoretinopathy." (PMID 39357823, 2024). "Autosomal dominant neovascular inflammatory vitreoretinopathy (ADNIV) is a rare autoimmune condition caused by mutations in CAPN5, typically diagnosed in adults, and characterized by intermediate uveitis, retinal degeneration and neovascularization." (PMID 37848930, 2023). "CAPN5 has been associated with autosomal dominant neovascular inflammatory vitreoretinopathy (ADNIV), obesity, Huntington’s disease, and polycystic ovary syndrome." (PMID 29245980, 2017). "Germline mutations in CAPN5 (Calpain 5), which encodes a calcium-dependent endopeptidase, have been associated with neovascular inflammatory vitreoretinopathy." (PMID 28193203, 2017). "CAPN5 mutations are the cause of Autosomal Dominant Neovascular Inflammatory Vitreoretinopathy (ADNIV, OMIM #602537), an inherited autoinflammatory uveitis and vitreoretinal degeneration without systemic features." (PMID 25216694, 2014). "CAPN5 has been linked to autosomal dominant neovascular inflammatory vitreoretinopathy (ADNIV)." (PMID 29245980, 2017). "CAPN5 mutations have been linked to autosomal dominant neovascular inflammatory vitreoretinopathy (ADNIV), a blinding autoimmune eye disease." (PMID 25856303, 2015). "In two large, unrelated kindreds we recently identified the first mutation shown to cause nonsyndromic uveitis: coding mutations in CAPN5 caused an inherited uveitis called autosomal dominant neovascular inflammatory vitreoretinopathy (ADNIV, OMIM #602537)." (PMID 25856303, 2015). "The purpose of this project was to identify short hairpin RNA (shRNA) sequences that can suppress expression of human CAPN5 in which gain-of-function mutants cause autosomal dominant neovascular inflammatory vitreoretinopathy (ADNIV)." (PMID 25216694, 2014). "Our data provide new relevance for neovascular inflammatory vitreoretinopathy (NIV), a progressive eye disease caused by pathogenic mutations in CAPN5." (PMID 40650235, 2025). "CAPN5 Neovascular Inflammatory Vitreoretinopathy (CAPN5-NIV; OMIM 193235) is a poorly-understood rare, progressive inflammatory intraocular disease with limited therapeutic options." (PMID 31110225, 2019). "Autosomal dominant neovascular inflammatory vitreoretinopathy (ADNIV) is caused by single point mutations in the CAPN5 gene (OMIM #602537), which causes the CAPN5 protease to become hyperactive." (PMID 29157313, 2017). "It will be important to determine whether any CAPN5 polymorphisms are risk factors for patients with the ADNIV-like diseases, such as uveitis, diabetic retinopathy, retinitis pigmentosa, or proliferative vitreoretinopathy." (PMID 25856303, 2015).
neuroblastoma (4 papers, 2014 to 2026). Neuroblastoma (NB) is the most common solid, extracranial childhood tumor. "To identify such neo-N-termini generated by CAPN5, we employed an N-terminomics approach called TAILS (Terminal amine isotopic labeling of substrates) to quantitatively compare the N-terminal peptides detected in parental and CAPN5-deficient SH-SY5Y neuroblastoma cells." (PMID 40650235, 2025). "We also have been found that overexpression of CAPN5 vectors shortened neurite lengths in mouse neuroblastoma N2A cells when compared to empty vector control transfection (data not shown)." (PMID 29245980, 2017). "Human SH-SY5Y neuroblastoma cells, transfected with full-length catalytically dead (Cys81Ala) CAPN5-3×FLAG, were used for anti-FLAG co-immunoprecipitation (co-IP) and quantitative proteomics using Sequential Window Acquisition of all THeoretical mass spectra (SWATH-MS)." (PMID 41597217, 2026). "This study identified 24 unique proteins and closely related members of five protein families as candidate substrates of CAPN5 by comparing the N-terminomes of parental and CAPN5−/− SH-SY5Y neuroblastoma cells." (PMID 40650235, 2025). "In contrast to HEK293T cells, the human neuroblastoma cell line SH-SY5Y expresses native CAPN5 and has been used to study CAPN5 protein expression." (PMID 25216694, 2014).
Blindness (3 papers, 2012 to 2019). Blindness is the condition of lacking visual perception defined as a profound reduction in visual perception. "Short Hairpin RNA interference is an effective method for reducing CAPN5 gene expression and may address other gain-of-function disease alleles that cause human blindness." (PMID 25216694, 2014). "Further validation of these novel biomarkers and drug targets will improve our understanding of molecular mechanisms underlying CAPN5-NIV and potentially point to therapies for more common causes of blindness." (PMID 31110225, 2019).
meningioma (3 papers, 2017 to 2024). A generally slow growing tumor attached to the dura mater. "Of the two mutations in the grade I meningioma, one (EPHB3) mutation was verified by Sanger sequencing, and of the nine mutations in the grade II tumor, two (CAPN5 and ADAMTSL3) were verified by Sanger sequencing." (PMID 28193203, 2017). "Further study of ADAMTSL3 and CAPN5 may lead to elucidation of their molecular implications in meningioma pathogenesis." (PMID 28193203, 2017). "In addition, we identified two candidate driver genes, CAPN5 and ADAMTSL3, which could contribute to the elevated growth rate of the grade II meningioma." (PMID 28193203, 2017).
uveitis (3 papers, 2015 to 2024). An inflammatory process affecting a part of or the entire uvea. "Early testing for CAPN5 gene in at risk children, and regular scheduled screening for uveitis and vasculitis will lead to prompt intervention." (PMID 37848930, 2023). "Specifically, calpain-2 has been connected to NIV, cataractogenesis, and glaucoma, while calpain-5 was associated with NIV and uveitis." (PMID 38303059, 2024). "This is the third case of a CAPN5 mutation leading to inherited uveitis and neovascular vitreoretinopathy, suggesting patients with ADNIV features should be tested for CAPN5 mutations." (PMID 25856303, 2015). "A candidate isoform may be calpain-5 which was shown to be expressed in the retina and found to be involved in inherited forms of uveitis." (PMID 38303059, 2024).
autoimmune uveitis (2 papers, 2012 to 2024). An autoimmune form of uveitis (disease). "CAPN5 mutations are associated with autoimmune uveitis, retinal neovascularization, and photoreceptor degeneration." (PMID 38650847, 2024).
breast carcinoma (2 papers, 2017 to 2024). "CAPN5 RNA probes were validated on mouse breast cancer tumor tissue." (PMID 29157313, 2017). "To examine whether CAPN5 cleaves c-Myc and STAT3 in vitro, we produced recombinant murine CAPN5 proteins with a C-terminal Myc-His (MH) tag in the human breast cancer cell line MCF-7." (PMID 39357823, 2024).
endometriosis (2 papers, 2013 to 2023). The growth of functional endometrial tissue in anatomic sites outside the uterine body. "Most importantly, the expression of calpain 6, a non-classical calpain, is increased in leiomyosarcomas, while the expression of calpain 5 is decreased in endometriosis." (PMID 23855590, 2013). "The CAPN5 gene was found to be underexpressed in eutopic endometrial biopsies of women with endometriosis when compared to controls without the disease." (PMID 36901866, 2023).
hepatoma (2 papers, 2018 to 2023). "Comparison of the absolute CAPN5 abundance with the enrichment from the CD81 IP suggests that a large fraction of CAPN5 is associated with CD81 in human hepatoma cells." (PMID 30024968, 2018). "Knockout of CD81 almost completely abrogated susceptibility of human hepatoma cells to HCV.Taken together we find that the CD81 interaction partners CAPN5 and CBLB are HCV host dependency factors." (PMID 30024968, 2018). "Finally, we report a whole cell proteome expression dataset for human hepatoma cells and show that CAPN5 is strongly associated with CD81." (PMID 30024968, 2018). "Expression in lung, kidney and brain was previously reported and we demonstrate CAPN5 expression in primary hepatocytes and hepatoma cells." (PMID 30024968, 2018). "While we discovered CAPN5 as CD81 interaction partner in hepatoma cells and primary human hepatocytes, we included CBLB as a hit from the STRING network analysis." (PMID 30024968, 2018). "Moreover, CAPN5 and CBLB appear to be strongly associated with the CD81 complex as their total abundance in human hepatoma cell lysates was comparably low as quantified by intensity based absolute quantification (iBAQ)." (PMID 30024968, 2018). "A proteomic analysis mapped 33 host protein interactions of CD81 in primary human liver and hepatoma cells, including for example protein CAPN5 (calpain-5) and ubiquitin ligase CBLB (Casitas B-lineage lymphoma proto-oncogene B), capable of forming a complex with CD81 and implicated in HCV entry." (PMID 37046846, 2023). "CAPN5 and CBLB were dispensable for CoV and VSV infection in human hepatoma cells." (PMID 30024968, 2018). "Neither CAPN5 nor CBLB affected surface expression of SCARB1, CD81, CLDN1 and OLCN on human hepatoma cells." (PMID 30024968, 2018). "In line with this, we demonstrate that CAPN5 and CBLB promote HCV entry, but not Plasmodium entry into human hepatoma cells." (PMID 30024968, 2018).
Hypertension (2 papers, 2007 to 2015). The presence of chronic increased pressure in the systemic arterial system. "Genetic association studies, for example, have identified CAPN5 variants that are risk factors for type II diabetes, hypertension, high cholesterol, and polycystic ovary syndrome." (PMID 25856303, 2015). "Here we present the first population-based association analysis of CAPN5 gene in traits related to hypertension and other components of metabolic syndrome." (PMID 17227582, 2007). "Results obtained from our analysis in PCOS women and this population-based study suggest that CAPN5 is a gene related to metabolic syndrome and related phenotypes such as obesity, hypertension and hypercholesterolemia, at least in the Spanish population." (PMID 17227582, 2007). "In addition, we identified several CAPN5 alleles associated with phenotypic differences observed between PCOS patients, such as the presence of obesity, cardiovascular complications, and familial antecedents of obesity, hypertension and T2DM aggregation." (PMID 17227582, 2007). "In addition, we associated several CAPN5 haplotypes with phenotypic differences observed between PCOS patients, such as the presence of obesity (AA-CA) and familial antecedents of obesity (AA-CA and GG-CG), hypertension (AA-CA and GG-CG) and hypercholesterolemia (GG-CA)." (PMID 17227582, 2007).
metabolic syndrome (2 papers, 2007 to 2008). A cluster of metabolic risk factors for CARDIOVASCULAR DISEASES and TYPE 2 DIABETES MELLITUS. "Anyway, the identification of CAPN5 gene haplotypes affecting cardiovascular risk factors also in general population reinforce CAPN5 as a candidate gene for metabolic syndrome related phenotypes." (PMID 17227582, 2007). "In this new study, we have analysed the association of four CAPN5 gene variants(rs948976A>G, rs4945140G>A, rs2233546C>T and rs2233549G>A) with several cardiovascular risk factors related to metabolic syndrome in general population." (PMID 17227582, 2007). "In addition, a CAPN5 haplotype over-represented in obese individuals is also associated with the cluster of cardiovascular risk factors defined as metabolic syndrome." (PMID 17227582, 2007). "However, a confirmation of our findings in independent populations is necessary to clearly establish the role of CAPN5 in metabolic syndrome." (PMID 17227582, 2007). "In these studies, we found that specific CAPN5 haplotypes could modify the risk of developing metabolic syndrome and PCOS, a common endocrine disorder in women of reproductive age in which all components of metabolic syndrome are frequent." (PMID 18657264, 2008). "Our results also may suggest CAPN5 as a candidate gene for metabolic syndrome." (PMID 17227582, 2007).
Obesity (2 papers, 2007 to 2008). Accumulation of substantial excess body fat. "Thus, this polymorphism, which is predicted to encode a stop codon in one of the CAPN5 mRNAs identified so far, doesn't seem to be a functional variant involved in obesity." (PMID 18657264, 2008). "With this purpose, we have selected highly informative polymorphisms in CAPN5, PPARG and PPARD genes and analysed it in 1953 individuals in relation to the absence or presence of obesity." (PMID 18657264, 2008). "In addition, we have found a significant interaction between CAPN5 and PPARD genes (p = 0.038) that reduces the risk for obesity in a 55%." (PMID 18657264, 2008). "Genetic association analysis of CAPN5 and PPARD gene variants with obesity." (PMID 18657264, 2008). "The association analysis at the CAPN5 did not contribute to elucidate if this gene has, per se, a role in obesity, since we did not found statistical significant differences at this locus between controls and cases (p ≥ 0.126)." (PMID 18657264, 2008).
type II diabetes (2 papers, 2012 to 2015). "Some polymorphisms in CAPN10 and CAPN5 have been shown to be risk factors for type II diabetes." (PMID 23055945, 2012).
Abdominal obesity (1 paper, 2007). Excessive fat around the stomach and abdomen. "We have not found evidence of association of CAPN5 alleles with abdominal obesity estimated by waist circumference." (PMID 17227582, 2007).
Autoimmunity (1 paper, 2017). The occurrence of an immune reaction against the organism's own cells or tissues. "There is also an evidence have been reported that the mutant R243L increased activation of CAPN5 catalytic core domain to stimulate TLR4 autoimmunity inflammation in CAPN5R243L transgenic mice retina." (PMID 29245980, 2017).
COVID-19 (1 paper, 2023). A disease caused by infection with severe acute respiratory syndrome coronavirus 2. "Indeed, different proteins associated to viral infection like the Long-chain Acyl-CoA synthetase 1 (ACSL1), Calpain-5 (CAPN5) or Syntaxin 10 (STX10), appeared down-regulated in ECFCs after stimulation with the serum of COVID-19 positive individuals." (PMID 37063416, 2023). "The last two, CAPN5 and STX10, were identified by predictive tools as highly discriminating proteins between ECFCs treated with “infected” serums and ECFCs incubated with COVID-19 negative serums (ECFCs+Neg)." (PMID 37063416, 2023).
deafness (1 paper, 2025). An inherited or acquired condition characterized by the complete loss of the ability to hear from one or both ears. "A variant in a gene that encodes another CAPN5 substrate candidate, SPTBN4, was reported to cause neurodevelopmental disorder with hypotonia, neuropathy and deafness." (PMID 40650235, 2025).
emphysema (1 paper, 2024). "To demonstrate the effect of CSE on CAPN5 in vivo, we established experimental emphysema mouse models by intraperitoneal injection of CSE19." (PMID 38650847, 2024). "In lung specimens of emphysema mice, IHC showed that CAPN5 was located in the bronchial epithelium, and its expression was markedly decreased in the emphysema group compared with the control group." (PMID 38650847, 2024). "Our results demonstrate that CAPN5 is significantly decreased in lung samples of COPD patients and emphysema mice, as well as in CSE-treated BEAS-2B cells." (PMID 38650847, 2024). "CAPN5 was mainly expressed in the airway epithelium and significantly decreased in the COPD-smoker and emphysema-mouse groups." (PMID 38650847, 2024). "We observed significant decreases in CAPN5 in COPD-smokers, emphysema mice, and CSE-treated BEAS-2B cells." (PMID 38650847, 2024).
endometrial cancer (1 paper, 2024). Primary or metastatic malignant neoplasm involving the endometrium (mucous membrane that lines the endometrial cavity). "For instance, CAPN5 plays a significant role in glycolysis in pancreatic cancer and endometrial cancer." (PMID 38902676, 2024).
hepatitis C virus infection (1 paper, 2020). A viral infection caused by the hepatitis C virus. "During hepatitis C virus infection, the ubiquitin ligase, Casitas B-lineage lymphoma proto-oncogene B forms a complex with another cellular factor, calpain-5 and the hepatitis C virus entry factor CD81 to support the virus entry into liver cells." (PMID 32544190, 2020).
promyelocytic leukemia (1 paper, 2017). "Though the role of the protein in neoplastic transformation is unclear, a recent study reported association of CAPN5 with promyelocytic leukemia nuclear bodies, which are involved in transcriptional regulation, cell differentiation, apoptosis, and cell senescence." (PMID 28193203, 2017).
retinal degeneration (1 paper, 2017). Degeneration of the retina. "Taken together, these findings strongly suggest that CAPN5 activation causes retinal degeneration and is also involved in neuronal degeneration." (PMID 29245980, 2017).
retinal disease (1 paper, 2019). "Although several CAPN5-NIV-causing mutations have been identified, it is unclear how a hyperactive protease leads to retinal disease." (PMID 31110225, 2019).
schizophrenia (1 paper, 2015). A major psychotic disorder characterized by abnormalities in the perception or expression of reality. "Although not directly related to calcium channels, it is of interest that in another whole exome sequencing study in schizophrenia, disruptive mutations were identified in members of the postsynaptic density gene set, including the gene for a calcium activated protease (CAPN5)." (PMID 26386135, 2015).